RNU7-46P (RNA, U7 small nuclear 46 pseudogene)
Synonyms: U7.46
Gene: Small nuclear RNA gene on chromosome 2 (98,840,675 to 98,840,736, reverse strand). Ensembl gene ENSG00000238830.
Homologues: Orthologues: chimpanzee U7 (98% identical). Paralogues in human: RNU7-3P (92% identical), RNU7-11P (89% identical), RNU7-25P (87% identical), RNU7-47P (85% identical), RNU7-4P (85% identical), RNU7-7P (85% identical), RNU7-13P (84% identical), RNU7-14P (84% identical), RNU7-22P (84% identical), RNU7-27P (84% identical), RNU7-28P (84% identical), RNU7-6P (84% identical), and 142 more.